GNAQP1 (G protein subunit alpha q pseudogene 1)
Synonyms: formerly GNAQP
Gene: Transcribed processed pseudogene on chromosome 2 (131,423,801 to 131,424,867, reverse strand). Ensembl gene ENSG00000214077.
Diseases named in the same sentence as GNAQP1 in open-access papers:
GNAQP1 is named in the same sentence as 1 disease in open-access papers, as found by Europe PMC text mining. Sharing a sentence is not in itself a finding about the gene and the disease.
GNAQP1 shares sentences with these, for which no sentence is quoted: tumor (1 paper).